GLTC1 (glycolysis associated regulator of LDHA post-transcriptional modification 1)
Synonyms: lnc-UNC93B1-1; GLTC
Gene: Long non-coding RNA gene on chromosome 11 (68,024,809 to 68,030,461, reverse strand). Ensembl gene ENSG00000255306.
Diseases named in the same sentence as GLTC1 in open-access papers:
GLTC1 is named in the same sentence as 3 diseases in open-access papers, as found by Europe PMC text mining. Sharing a sentence is not in itself a finding about the gene and the disease.
GLTC1 shares sentences with these, for which no sentence is quoted: papillary thyroid cancer (1 paper); thyroid cancer (1); tumor (1).